GIP (gastric inhibitory polypeptide)
Diseases named in the same sentence as GIP in open-access papers (continued):
Sharing a sentence is not in itself a finding about the gene and the disease.
Obesity (continued). "Thus, the aim of this research work was to unravel the potential effects of gut peptide hormones on human AT by characterizing the effects of GLP-1, GIP and glucagon on VAT exometabolomic profiles pertaining to individuals with obesity across different glycemic statuses." (PMID 37233628, 2023). "Moreover, SCFA-mediated GPCR activation in the gut could induce the secretion of the endocrine hormones GLP-1, PYY, and glucose-dependent insulinotropic polypeptide (GIP), which have been proven to be important in preventing or treating obesity." (PMID 38299183, 2023). "Recent contemporary advances in the treatment of obesity and diabetes has also guided the development of co‐agonistic approaches to drug therapy such as GLP‐1/glucagon, glucose‐dependent insulinotropic polypeptide (GIP)–GLP1, amylin–calcitonin dual agonists, and GIP–GLP1–glucagon tri‐agonists." (PMID 37034567, 2023). "Particularly, it warrants clarification whether GIP may even improve lipid metabolism independent of its ability to reduce obesity and hyperglycemia." (PMID 37592302, 2023). "A very powerful GIP/GLP-1 co-agonist, tirzepatide is currently under clinical development; this compound results in large weight losses in people with diabetes and losses exceeding 20% in people with obesity (Lilly, press release May 2022)." (PMID 35990325, 2022). "However, we found that it produced resistance to diet-induced obesity (DIO) via non-cell-autonomous mechanisms involving GIP." (PMID 35017517, 2022). "Although the clinical success of these agents has laid the foundation for a new era of anti-obesity drugs, there is considerable debate as to how GLP1/GIP regulates metabolism and whether its receptor agonists or antagonists can be the drugs of choice for treating obesity and T2DM." (PMID 35630534, 2022). "We previously investigated the effects of absent and 50% reduced GIP secretion on HFD-induced obesity and insulin resistance using GIP-knockout mice; we found that reduced GIP secretion as well as absent GIP secretion alleviates fat mass gain and insulin resistance under HFD feeding condition." (PMID 31977316, 2020). "Taken together, these findings suggest that GIP at pharmacological concentrations could exert protective effects against atherosclerosis without deteriorating the obesity, and the beneficial effects of GIP might also be preserved in diabetic animals." (PMID 32098413, 2020). "Nevertheless, the mechanism of GIP-stimulated adipocyte lipolysis, rather than triglyceride storage, could potentially be an anti-obesity mechanism for pharmacological doses of GIPR agonists to overcome the anti-lipolytic effects of insulin." (PMID 33020469, 2020). "On the other hand, we previously reported that both wild-type (WT) and GIP receptor-deficient (GiprKO) mice fed a high-starch, low-protein diet (HSTD), show a body weight gain, compared with those fed normal chow (NC), indicating that HSTD induces obesity in a manner independent of the GIP signal." (PMID 31083314, 2019). "However, in contrast to the well-defined action of GIP on adipose tissues, the regulatory mechanism of GIP secretion in the context of obesity has not been fully clarified." (PMID 31509948, 2019). "Further investigation might shed light on the molecular mechanisms underlying GIP action in fat accumulation and might open up a possibility of GIP-based antidiabetic therapy that does not promote obesity." (PMID 26075286, 2015). "Because fructose elicits GLP-1 secretion without simultaneous release of glucagonotropic GIP, the pathways underlying fructose-stimulated GLP-1 release might be useful targets for type 2 diabetes mellitus and obesity drug development." (PMID 24525020, 2014).
Obesity (continued). "In view of the glucose intolerance but resistance to diet-induced obesity observed in GIPR knockout mice, the current study was initiated to test the hypothesis that chronically elevating GIP levels in vivo would increase adipose tissue expansion and exert beneficial effects on glucose homeostasis." (PMID 22802954, 2012). "The current break-fix healthcare models do not align with the chronicity of clinical obesity and must be augmented with accessible, sustainable, and effective post-treatment models of care to maintain the positive weight outcomes associated with GLP-1/GIP RA class medications." (PMID 40332727, 2025). "While the physiologic GIP action to potentiate insulin secretion and improve glycemia in healthy volunteers suggests pharmacologic agonism as a means to treat metabolic disease, this argument is not wholly commended by studies of patients with obesity and/or T2D." (PMID 40507574, 2025). "Thus, with continuing development on GIP/GLP-1R co-agonists modalities, it is hoped that clarity can be ascertained as to whether GIPR agonism or antagonism has the greatest role to play in management of obesity and related metabolic diseases." (PMID 38861364, 2024). "While some research views GIP’s action as beneficial and suggests that it could aid in the growth of healthy SAT depots, other studies claim that it may support the expansion of healthy SAT depots, whereas other studies consider GIP as an endogenous hormone that promotes obesity in AT." (PMID 39201336, 2024). "Thus, TZT, through activation of both GIP and GLP-1, may reduce obesity-mediated inflammation." (PMID 37208555, 2023). "However, gut microbiota alterations have been shown to influence incretin sensitivity in obesity, insulin resistance, and T2D; therefore, elevated GLP-1 and GIP levels may be reflective of a compensatory response that ultimately fails to promote β-cell function." (PMID 33467110, 2021). "Therefore, development of therapies based on dual and triple co-agonists of GLP-1, GIP and glucagon receptors might be of interest, not only for T2D or obesity but also for NAFLD/NASH; however, more studies are needed." (PMID 32823659, 2020). "However, the secretion of GIP does not seem to be affected by T2DM or obesity." (PMID 32825608, 2020). "Randomized and observational studies including patients aged 6-19 years with overweight or obesity, with or without T2D, treated with GLP-1 RAs or dual GIP/GLP-1 agonists, were included." (PMID 42280306, 2026). "Numerous clinical studies have evaluated the effects of GLP-1RAs, as well as the dual GIP/GLP-1 RA tirzepatide, on gastric emptying as a primary or secondary endpoint in subjects with T2D and those with obesity but without diabetes." (PMID 39568409, 2024). "The recruitment of subjects stratified by insulin sensitivity allowed us to uniquely examine the combined effects of obesity and insulin resistance on glucagon, GLP-1, and GIP secretion, which has not been previously characterized in pediatric studies." (PMID 38087928, 2024). "In summary, although we were not able to fully revert the altered phenotype, GLP-1, GIP and glucagon did improve the metabolic profile of the VAT of subjects with obesity and prediabetes." (PMID 37233628, 2023). "Individuals with obesity had higher levels of Gal-4, were older, had a higher BMI, higher levels of NT-proBNP, GIP, triglycerides, insulin, and FPG, along with higher HOMA-IR, compared to individuals without obesity." (PMID 37985679, 2023). "Tirzepatide (LY3298176, Mounjaro) is the first dual GIP and GLP-1 RAs for the treatment of T2DM, obesity, and nonalcoholic steatohepatitis." (PMID 37141329, 2023). "However, the apparent lack of GIP efficacy in patient with T2D coupled with the obesity protective phenotype of GIPR knockout mice, initially discouraged the development of GIPR agonists for diabetes therapy and even suggested that development of GIPR antagonists might be expedient." (PMID 35846282, 2022).
Obesity (continued). "In conclusion, three months caloric restriction improved some metabolic parameters in obese patients with lower (<29 pg/mL) plasma GIP level but did not influence these same metabolic parameters in obese patients with higher GIP level, which may reflect early metabolic complications in obesity." (PMID 36010335, 2022). "GIP secretion increases with obesity, but there does not seem to be a correlation between T2DM and GIP secretion." (PMID 33339298, 2020). "Tirzepatide (Mounjaro®), a dual glucose-dependent insulinotropic peptide/glucagon-like peptide 1 (GIP/GLP1) receptor agonist, was recently approved for diabetes management as well as weight reduction for nondiabetic individuals with obesity or overweight and weight-related health problems." (PMID 40302276, 2025). "In patients with obesity and diabetes (OB+/DM+), neither GLP-1 (66.31% ± 30.11%, n = 7) nor GIP (71.74% ± 32.57%, n = 8) significantly altered BTCH-induced contraction in longitudinal muscle strips compared to control (vehicle-treated, 74.08% ± 18.93%, n = 8; P > 0.05)." (PMID 41561152, 2025). "Until recently GIP had not been developed as a therapeutic and thus has been overshadowed by the other incretin, glucagon-like peptide 1 (GLP-1), which is the basis for several successful drugs to treat diabetes and obesity." (PMID 40024571, 2025). "The aim of this study was to observe the effects of RYGB surgery on intestinal morphology as well as the differential expression of four major gut hormones GIP, GLP-1, GLP-2 and PYY in the BPL compared with the AL in normal rats as well as rats with diet-induced obesity." (PMID 37228045, 2023). "In addition, although our study suggests that GIP has both proliferative and anti-apoptotic effects on β-cells in response to HFD stresses, the mice in the present study showed obesity but did not develop diabetes during the 10-week observation period." (PMID 35909510, 2022). "These promising data suggest that it may not take too long until the first GLP-1/GIP/GCG triple receptor agonist passes registration and enters the market for the treatment of obesity and diabetes." (PMID 36552107, 2022). "Furthermore, because fructose elicits GLP-1 secretion without simultaneous release of glucagonotropic GIP, the pathways underlying fructose-stimulated GLP-1 release might be useful targets for drug development aiming at stimulating GLP-1 secretion for the treatment of type 2 diabetes and obesity." (PMID 24525020, 2014). "In patients with obesity but without diabetes (OB+/DM−), no significant changes in longitudinal muscle contraction were observed following incubation with either GLP-1 (78.87% ± 30.47%, n = 6) or GIP (66.20% ± 22.02%, n = 6) when compared to control (84.38% ± 28.92%, n = 6; P > 0.05)." (PMID 41561152, 2025). "Some studies were also conducted in patients with obesity or metabolic syndrome, showing that acute administration of β-glucan enriched foods dose-dependently increases PYY, increases CCK without affecting ghrelin, or decreases GIP without affecting insulin, GLP-1, or ghrelin." (PMID 36832775, 2023). "However, neither mice administered long acting analogs of GIP1–42 nor GIP-overexpressing transgenic mice exhibit increases in body weight, food intake, adiposity or insulin resistance, questioning whether GIPR agonists would promote obesity in patients with type 2 diabetes." (PMID 20231880, 2010).
type 2 diabetes (302 papers, 2008 to 2026). "Among several anti-diabetic medications, a systemic analysis reveals that GLP1-RAs and dual GLP-1/Gastric inhibitory polypeptide (GIP) agonists such as tirzepatide are most effective at causing weight loss in patients with type 2 diabetes." (PMID 37333802, 2023). "On the contrary, F-moHF showed increased circulating levels of ghrelin and GIP compared to F-moC and to M-moHF, which correlates to insulin sensitivity, associated with a reduction of type II diabetes pathway activity." (PMID 36195702, 2022). "Co-localisation analysis showed evidence of a shared causal variant for type 2 diabetes liability and eight outcomes at the GIP gene, and six outcomes at the GIPR gene (PP > 0.8)." (PMID 34505161, 2021). "There was evidence of a larger association of genetically proxied GIP signalling compared with genetically proxied reduced type 2 diabetes liability more generally for CRP, HDL-C and triacylglycerol levels (all p < 0.001), but not strongly for BMI (p = 0.07)." (PMID 34505161, 2021). "Evidence of co-localisation with genetic associations of type 2 diabetes liability at both the GIP and GIPR genes was observed for five outcomes." (PMID 34505161, 2021). "GIP is associated with the pathophysiology of obesity and type 2 diabetes mellitus (T2D) and have therefore been the focus of therapeutic interest for many years." (PMID 34760890, 2021). "Meanwhile, efforts were made to explore if there was a possible association between GIP gene variants and the risk of type 2 diabetes." (PMID 28840129, 2017). "The decline in beta cell function in type 2 diabetes is in directly associated with impaired action of the incretin hormones, glucose-dependent insulinotropic polypeptide (GIP), and GLP-1." (PMID 23737653, 2013). "Though we did not observe any significant association of the studied polymorphisms with type 2 diabetes in our study population, we suggest a detailed genetic analysis of SNPs in GIP in other Asian populations as well." (PMID 20673334, 2010). "So it is important to use a larger study group and also a different population before ruling out the possible association of GIP with type 2 diabetes." (PMID 20673334, 2010). "In this study, we did a case-control analysis of common variants (rs2291726 and rs2291725) in GIP with type 2 diabetes in a South Indian population." (PMID 20673334, 2010). "Since the role of GIP in the manifestation of type 2 diabetes seems to be different among Europeans and Asians it is important to replicate association studies of GIP in Asian population as well." (PMID 20673334, 2010). "The aim of our study was to do a case-control association analysis of common variants in GIP in association with type 2 diabetes and related biochemical parameters." (PMID 20673334, 2010). "GLP-1 receptor agonists have become increasingly central to type 2 diabetes management, with tirzepatide, an agent with dual incretin activity (gastric inhibitory polypeptide (GIP)/GLP-1 agonism), showing superior weight loss and glycemic control compared to other GLP-1 analogs." (PMID 41458667, 2025). "We examined whether genetic associations for type 2 diabetes liability in the GIP and GIPR genes co-localised with genetic associations for 11 cardiometabolic outcomes." (PMID 34505161, 2021). "Potassium voltage-gated KQT-like (KCNQ1) channels play a role in the intestinal secretion of GLP-1 and glucose-dependent insulinotropic polypeptide (GIP), and polymorphisms in the gene coding for these channels have been linked to type 2 diabetes through a role in insulin release." (PMID 33594477, 2021). "There is some renewed interest in GIP-based drugs, especially when co-administered with GLP-1 (GIP/GLP-1 co-agonists) with studies suggesting that both GIP agonism and GIP antagonism may facilitate weight loss in type 2 diabetes." (PMID 33897622, 2021).
type 2 diabetes (continued). "GIP is known for its adipogenic properties in addition to its incretin function, and has been implicated in the connection between high fat diets and the risk of metabolic abnormalities including insulin resistance and type 2 diabetes." (PMID 31921879, 2019). "Further functional and prospective studies on the GIP gene are required before GIP polymorphisms could be used as predictors of CAD risk in patients with type 2 diabetes in the Chinese Han population." (PMID 29765988, 2018). "Increased GIP release leads to increased insulin secretion that causes insulin insensitivity and type 2 diabetes mellitus (T2DM)." (PMID 35224107, 2022). "Relevant to GIP–GLP-1 interaction is evidence that GIP receptor gene polymorphisms can alter receptor signalling sufficiently to modify the risk and progression of type 2 diabetes." (PMID 41174263, 2026). "Semaglutide and tirzepatide are two commonly prescribed glucagon-like peptide-1 (GLP-1) and GLP-1/glucose-dependent insulinotropic polypeptide (GLP-1/GIP) receptor agonists used for the treatment of type 2 diabetes and chronic weight management." (PMID 41210042, 2025). "In agreement with an anabolic role of GIP on bone formation, infusion of GIP decreases markers of bone resorption in healthy humans, postmenopausal women, and in people with type 1 or type 2 diabetes." (PMID 40024571, 2025). "Here we overview the glucose-lowering and weight-reducing effects of incretin-based therapies, discussing the effective and safety use of DPP-4 inhibitors, GLP-1 RAs, and GIP/GLP-1 receptor agonist tripeptide in Japanese individuals with type 2 diabetes." (PMID 40607140, 2025). "The half-life of intact, physiologically active GIP is approximately 7 min in healthy individuals and 5 min in patients with type 2 diabetes." (PMID 40649920, 2025). "Glucagon-like peptide-1 (GLP-1) and glucose-dependent insulinotropic polypeptide (GIP) receptor agonists (RAs) are a class of drugs used in type 2 diabetes management." (PMID 40746803, 2025). "On the other hand, in people with type 2 diabetes, the incretin effect—including GIP response—is almost entirely lost." (PMID 40362890, 2025). "The clearance rate of intact GIP and its metabolite is comparable between obese patients with type 2 diabetes and healthy individuals." (PMID 40649920, 2025). "On the other hand, although the glucoregulatory effects of GLP-1 remain intact in individuals with type 2 diabetes, the immediate insulinotropic impact of native GIP is significantly reduced in diabetic patients." (PMID 40649920, 2025). "The results indicated that SCGN and GIP levels increased postprandially in both groups, with a particularly pronounced rise noted in patients with type 2 diabetes." (PMID 40012909, 2025). "Tirzepatide is a novel GLP-1RA / gastric inhibitory polypeptide (GIP) co-agonist licensed for treatment of type 2 diabetes." (PMID 40637847, 2025). "The authors concluded that the serum concentrations of GIP and PP were lower in pancreatic cancer patients regardless of the degree of glucose intolerance compared with patients with type 2 diabetes and the healthy individuals in the control group." (PMID 39596226, 2024). "A prespecified meta-analysis of the clinical development program for the dual GIP/GLP-1 receptor co-agonist tirzepatide concluded that tirzepatide did not increase major cardiovascular events in participants with Type 2 diabetes." (PMID 39582036, 2024). "Metabolic phenotyping studies showed that acute or chronic stimulation of K cell Gs signaling greatly improved impaired glucose homeostasis in obese mice and in a mouse model of type 2 diabetes, due to enhanced GIP secretion." (PMID 39436694, 2024). "While considering the benefits of GLP-1 and GIP/GLP-1 receptor agonist therapy, caution is needed in clinical scenarios for discontinuation of drugs before procedures, as people with type 2 diabetes risk worsening diabetes control." (PMID 39768911, 2024).